ERCC2 (ERCC excision repair 2, TFIIH core complex helicase subunit)
Description:
ATP-dependent 5'-3' DNA helicase. Component of the general transcription and DNA repair factor IIH (TFIIH) core complex, not absolutely essential for minimal transcription in vitro. Required for transcription-coupled nucleotide excision repair (NER) of damaged DNA; recognizes damaged bases. Sequestered in chromatin on UV-damaged DNA. When complexed to CDK-activating kinase (CAK), involved in transcription by RNA polymerase II. In NER, TFIIH acts by opening DNA around the lesion to allow the excision of the damaged oligonucleotide and its replacement by a new DNA fragment. The ATP-dependent helicase activity of XPD/ERCC2 is required for DNA opening. Involved in DNA lesion verification. In transcription, TFIIH has an essential role in transcription initiation. When the pre-initiation complex (PIC) has been established, TFIIH is required for promoter opening and promoter escape. Phosphorylation of the C-terminal tail (CTD) of the largest subunit of RNA polymerase II by the kinase module CAK controls the initiation of transcription. XPD/ERCC2 acts by forming a bridge between CAK and the core-TFIIH complex. The structure of the TFIIH transcription complex differs from the NER-TFIIH complex; large movements by XPD/ERCC2 and XPB/ERCC3 are stabilized by XPA which allow this subunit to contact ssDNA. Involved in the regulation of vitamin-D receptor activity. As part of the mitotic spindle-associated MMXD complex it plays a role in chromosome segregation. Might have a role in aging process and could play a causative role in the generation of skin cancers.
Synonyms: XPD; MAG; EM9; MGC102762; MGC126218; MGC126219; COFS2; CXPD; TFIIH; TTD; TTD1
Tractability: Small molecule: a structure with a bound ligand is known; a high-quality ligand is known. PROTAC: UniProt records ubiquitination sites on it; ubiquitination databases record sites on it; its protein half-life has been measured; a small molecule that binds it is known.
Target class: Enzyme; Hydrolase
Safety:
Unwanted effects reported when the protein is acted on. In parentheses: how it was acted on, where the effect was seen, and who reports it.
Drug Toxicity (source: ClinPGx)
adverse events related to drug toxicities (source: ClinPGx)
alopecia (source: ClinPGx)
anemia (source: ClinPGx)
early relapse (source: ClinPGx)
leukopenia (source: ClinPGx)
longer survival times (source: ClinPGx)
nephrotoxicity (source: ClinPGx)
neutropenia (source: ClinPGx)
pneumonitis (source: ClinPGx)
progression free survival (source: ClinPGx)
shorter survival times (source: ClinPGx)
toxicities (source: ClinPGx)
Gene: Protein-coding gene on chromosome 19 (45,349,773 to 45,370,918, reverse strand). Ensembl gene ENSG00000104884.
Subcellular location: Nucleus; Cytoplasm, cytoskeleton, spindle
Subcellular location (Human Protein Atlas): Nucleoplasm; Cytosol
Pathways (Reactome):
Gene expression (Transcription): Formation of RNA Pol II elongation complex; Formation of the Early Elongation Complex; NoRC negatively regulates rRNA expression; RNA Pol II CTD phosphorylation and interaction with CE; RNA Polymerase I Promoter Escape; RNA Polymerase I Transcription Initiation; RNA Polymerase I Transcription Termination; RNA Polymerase II Pre-transcription Events; RNA Polymerase II Promoter Escape; RNA Polymerase II Transcription Elongation; RNA Polymerase II Transcription Initiation; RNA Polymerase II Transcription Initiation And Promoter Clearance; RNA Polymerase II Transcription Pre-Initiation And Promoter Opening
Disease: Formation of HIV elongation complex in the absence of HIV Tat; Formation of HIV-1 elongation complex containing HIV-1 Tat; Formation of the HIV-1 Early Elongation Complex; HIV Transcription Initiation; RNA Pol II CTD phosphorylation and interaction with CE during HIV infection; RNA Polymerase II HIV Promoter Escape; Tat-mediated elongation of the HIV-1 transcript; Transcription of the HIV genome
DNA Repair: Dual Incision in GG-NER; Dual incision in TC-NER; Formation of Incision Complex in GG-NER; Formation of TC-NER Pre-Incision Complex; Gap-filling DNA repair synthesis and ligation in TC-NER; Transcription-Coupled Nucleotide Excision Repair (TC-NER)
Metabolism: Cytosolic iron-sulfur cluster assembly
Metabolism of RNA: mRNA Capping
Gene Ontology:
Molecular function: 5'-3' DNA helicase activity; ATP hydrolysis activity; protein binding; protein-macromolecule adaptor activity; damaged DNA binding; DNA helicase activity; ATP binding; DNA binding; helicase activity; hydrolase activity, acting on acid anhydrides, in phosphorus-containing anhydrides; nucleic acid binding
Biological process: apoptotic process; chromosome segregation; hair cell differentiation; nucleotide-excision repair; regulation of mitotic cell cycle phase transition; regulation of transcription by RNA polymerase II; response to oxidative stress; transcription by RNA polymerase II; transcription initiation at RNA polymerase II promoter; transcription-coupled nucleotide-excision repair; positive regulation of mitotic recombination; embryonic organ development; response to hypoxia
Cellular component: CAK-ERCC2 complex; cytoplasm; MMXD complex; nucleoplasm; nucleus; spindle; transcription factor TFIID complex; transcription factor TFIIH core complex; transcription factor TFIIH holo complex
Genetic constraint (gnomAD): Loss-of-function variants: 89 observed, 97.49 expected, observed/expected ratio (o/e) 0.91, 90% interval 0.77 to 1.09. The upper end of that interval is the gene's LOEUF score, 1.09, which puts it in group 4 of 6, group 1 being the genes least tolerant of losing a copy. Missense variants: 992 observed, 1,045.9 expected, observed/expected ratio (o/e) 0.95, 90% interval 0.9 to 1. Synonymous variants: 496 observed, 438.15 expected, observed/expected ratio (o/e) 1.13, 90% interval 1.05 to 1.22.
Gene-disease validity (ClinGen):
ClinGen rates the evidence that ERCC2 causes each of these diseases.
xeroderma pigmentosum group D (autosomal recessive): Definitive.
Cancer hallmarks: escaping programmed cell death (suppresses); genome instability and mutations (suppresses)
Homologues: Orthologues: macaque ERCC2 (99% identical), chimpanzee ERCC2 (99% identical), pig ERCC2 (98% identical), rat Ercc2 (98% identical), guinea pig ERCC2 (98% identical), mouse Ercc2 (98% identical), dog ERCC2 (94% identical), rabbit ERCC2 (84% identical), zebrafish ercc2 (83% identical), tropical clawed frog ercc2 (80% identical), Drosophila melanogaster Xpd (69% identical), Caenorhabditis elegans xpd-1 (59% identical). Paralogues in human: RTEL1 (26% identical), DDX11 (24% identical), BRIP1 (23% identical).
Diseases named in the same sentence as ERCC2 in open-access papers:
ERCC2 is named in the same sentence as 184 diseases in open-access papers, as found by Europe PMC text mining. Sharing a sentence is not in itself a finding about the gene and the disease. The quoted sentences say what the papers report.
xeroderma pigmentosum (66 papers, 2008 to 2025). Xeroderma pigmentosum (XP) is a rare genodermatosis characterized by extreme sensitivity to ultraviolet (UV)-induced changes in the skin and eyes, and multiple skin cancers. "Homozygous mutations in ERCC2 are classically associated with the UV sensitivity conditions Xeroderma Pigmentosa and trichothiodystrophy, but have also been reported in approximately 11% of urothelial carcinomas and 2% of all solid tumors." (PMID 40563612, 2025). "We found three different P/LP variants in the ERCC2 gene only in BC patients, and the variants were previously defined in patients with xeroderma pigmentosum or trichothiodystrophy in a homozygote state." (PMID 39684352, 2024). "Deficiency of ERCC2 has been reported to lead to xeroderma pigmentosum (XP), trichothiodystrophy (TTD), and Cockayne’s syndrome (CS)." (PMID 36874118, 2023). "Xeroderma pigmentosum (XP) group D, a severe disease often typified by extreme sun sensitivity, can be caused by ERCC2 mutations." (PMID 32047639, 2020). "Mutations in the ERCC3 (XPB) or ERCC2 (XPD) genes can cause xeroderma pigmentosum (XP), trichothiodystrophy (TTD) and sometimes combined features of XP and Cockayne syndrome (CS)." (PMID 33196848, 2020). "As such, autosomal recessive ERCC2 germline mutations cause xeroderma pigmentosum (OMIM 278730) or trichothiodystrophy (OMIM 601675), both characterized by increased sensitivity to ultraviolet (UV) radiation and other skin abnormalities." (PMID 29684080, 2018). "XPD/ERCC2 belongs to the family of genes whose mutations lead in homozygotes to various forms of Xeroderma pigmentosum, here complementation group D (OMIM 278730)." (PMID 25951169, 2015). "We identified the previously reported K751Q polymorphism (rs13181) that eliminates an ubiquitination site in the ERCC2 protein and is associated with greater risk of melanoma, acute myeloid leukemia, and Xeroderma Pigmentosum." (PMID 26068475, 2015). "Mutations in human XPD (also known as ERCC2) mainly cause three clinical phenotypes: xeroderma pigmentosum (XP), Cockayne syndrome (XP/CS) and trichothiodystrophy (TTD), and only XP patients have a high predisposition to developing cancer." (PMID 25431422, 2015). "For example, the single disease gene ERCC2 causes both trichothiodystrophy and xeroderma pigmentosum." (PMID 25538735, 2014). "Most amino-acid substitution variants of ERCC2/XPD found in patients with xeroderma pigmentosum, Cockayne syndrome, and trichothiodystrophy occur in these regions." (PMID 21496236, 2011). "The literature describes multiple individuals in whom these two ERCC2 variants occur in cis and as part of a complex allele of compound heterozygous genotypes with other pathogenic alleles and features of xeroderma pigmentosum (XPD; OMIM #278730) and trichothiodystrophy (TTD1; OMIM #601675)." (PMID 37762649, 2023). "Based upon these data, we hypothesize that variations in the human XPD/ERCC2 gene might increase the susceptibility for several disorders besides Xeroderma pigmentosum in heterozygotes under particular environmental conditions." (PMID 25951169, 2015). "Mutations in ERCC2/XPD have been linked to multiple human genetic disorders, including xeroderma pigmentosum (XP), Cockayne syndrome (CS), and trichothiodystrophy (TTD)." (PMID 36065184, 2022). "ERCC2 could cause Xeroderma Pigmentosum when mutated in germ line." (PMID 27863412, 2016). "TTD is a distinct condition from Xeroderma Pigmentosum (XP) caused by mutation in eight XP‐associated genes: XPA, XPD (ERCC2), XPB (ERCC3), XPF (ERCC4), XPG (ERCC5), XPC, XPE (DDB2), and a variant form related to the POLH gene." (PMID 39976384, 2025). "Disease‐causing variants in ERCC2 can partially inactivate these activities, giving rise to symptoms seen in TTD, Cockayne syndrome (CS) and xeroderma pigmentosa (XP)." (PMID 39976384, 2025).
xeroderma pigmentosum (continued). "g.,ERCC2/XPD,ERCC3/XPB,ERCC4/XPF,ERCC5/XPG,ERCC6/CSB, andERCC8) in the NER pathway frequently cause Xeroderma pigmentosum, trichothiodystrophy, or Cockayne syndrome." (PMID 35593466, 2022). "BRCA2 and ERCC2 are also linked with classical cancer predisposition syndromes, hereditary breast and ovarian cancer (HBOC) and xeroderma pigmentosum (XP), respectively." (PMID 30871259, 2019). "Mutations in ERCC2/XPD have been associated with three hereditary diseases, namely Xeroderma pigmentosum (XP), Cockayne Syndrome and Trichothyodystrophy (TTD)." (PMID 26627042, 2015). "In ERCC2-deficiency, other NER genes partially compensate for the loss of XPD, thus explaining the milder clinical phenotype of TTD1 as compared to xeroderma pigmentosum (XP) with respect to defective DNA repair." (PMID 39055713, 2024). "The ERCC2 (excision repair cross-complementing rodent repair deficiency, complementation group 2) protein, which is also known as XPD, is involved in transcription-coupled nucleotide excision repair and is implicated in cancer-prone xeroderma pigmentosum, trichothiodystrophy, and Cockayne syndrome." (PMID 23157318, 2012). "Several xeroderma pigmentosum (XP) group genes are involved in NER, including group C (XPC), group D (ERCC2/XPD) and group G (ERCC5/XPG)." (PMID 27246611, 2016). "In humans, the defects in XPD/ERCC2 and XPB/ERCC3 genes lead to xeroderma pigmentosum (XP) and Cockayne's Syndrome (CS)." (PMID 21375739, 2011). "In the Fe–S helicases XPB (ERCC3) and XPD (ERCC2), recurrent missense mutations fall within the helicase core or the TFIIH-interacting interfaces, explaining the spectrum of transcription and repair defects underlying Xeroderma Pigmentosum (XP) and Trichothiodystrophy (TTD)." (PMID 41302153, 2025). "Biallelic pathogenic variants in one of the seven NER genes coding for the so-called complementation groups, XPA, ERCC3, XPC, ERCC2, DDB2, ERCC4, ERCC5, the NER gene ERCC1, and the gene coding for XP variant, POLH, are the causes of the rare hereditary disease Xeroderma pigmentosum (XP)." (PMID 35174087, 2022). "Xeroderma pigmentosum (XP) is a human autosomal recessive disease and is characterized by seven complementation groups from A through G. XPD/ERCC2 (Rad3 in Saccharomycescerevisiae), an ATP-dependent helicase, belongs to RAD3/XPD helicase subfamily." (PMID 25969448, 2015). "Worth noting is the fact that the ERCC2/XPD and ERCC5/XPG proteins are both involved in excision repair of UV-induced DNA damage and that photosensitivity is commonly observed in patients with xeroderma pigmentosum, Cockayne syndrome, and trichothiodystrophy." (PMID 21496236, 2011).
breast carcinoma (44 papers, 2005 to 2025). "Analysis of rare missense variants identified evidence of associations of TMEM161A, SIPA1L1, and ERCC2 with overall breast cancer, RNF175 and NCKAP1L with ER-positive disease, and SLC22A10, PHAX, SMARCA2, EML5, NTRK3, and MED23 with ER-negative disease." (PMID 35884425, 2022). "For patient BZ1 with subsequent onset of breast cancer and GC, the ERCC2 mutation coexisted with the MUTYH mutation." (PMID 34567566, 2021). "Cancer subtype based on our ANOVA results was significantly associated with the expression of all but 2 (ADH1C and ERCC2) alcohol-breast cancer risk related genes." (PMID 32078659, 2020). "Relatedly, we identified a patient (CCF02255) with ERCC2 frameshift truncating germline variant and breast cancer." (PMID 29684080, 2018). "The analysis of association between ERCC2-rs1799793 and clinicopathological features showed that women cases with homozygote AA genotype were more likely to have ER-positive and PR-positive breast cancer compared with women carrying the GG genotype." (PMID 29544444, 2018). "Our findings are a first observation of association between ERCC2 SNPs and breast cancer in Moroccan population." (PMID 29544444, 2018). "We identified 25 potential candidate mutations for cancer breast cancer susceptibility, some of them affecting ERCC2 functional activity in appropriate cell-culture based assays." (PMID 27504877, 2016). "While in the postmenopausal sub-cohort, ERCC1 rs11615 and ERCC2/XPD rs50872 were associated with increased breast cancer risk." (PMID 27768589, 2016). "This case-control association study revealed that ERCC1 rs11615 (T allele), XPC rs2228000 (T allele) and ERCC2/XPD rs50872 (T allele) were associated with increased breast cancer risk." (PMID 27768589, 2016). "The result showed that ERCC1 rs11615, XPC rs2228000, and ERCC2/XPD rs50872 carriers have a higher breast cancer risk in the whole study population." (PMID 27768589, 2016). "The aim of the present study was to test for an association between the Asn118Asn (ERCC1), Lys751Gln and Asp312Asn (ERCC2) variants, and osteosarcoma and colorectal and breast cancer in Mexican patients." (PMID 25789018, 2015). "This is the first study analyzing the SNPs in ERCC1 and ERCC2 genes and the susceptibility to cancer in Mexican-mestizo patients with osteosarcoma, and colorectal and breast cancer." (PMID 25789018, 2015). "It is known that the Gln/Gln homozygous variant of the ERCC2 gene has been associated with an increased risk of lung, skin, bladder, and breast cancer." (PMID 24402573, 2014). "The Gln/Gln variant of the ERCC2 gene has been associated with an increased risk of lung cancer, and correlated with higher risk of skin, bladder and breast cancer." (PMID 22544315, 2012). "Details of allele frequencies of the SNP rs13181 (ERCC2) observed in normal female and breast cancer samples." (PMID 19615095, 2009). "Representation of genetic association of the SNP rs13181 in the gene ERCC2 with the risk of breast cancer in terms of odds ratios of mutant genotypes." (PMID 19615095, 2009). "Statistically significant association with breast cancer susceptibility was observed for the mutant genotypes of the polymorphism rs13181 in the gene ERCC2 viz." (PMID 19615095, 2009). "The corresponding 3 × 2 contingency Chisquare value was 24.39 (P < 0.0001) for the genotypes of rs13181 (ERCC2) which suggested an overall significant association between breast cancer incidences and genotypes for the loci rs13181 (ERCC2)." (PMID 19615095, 2009). "Literatures evaluating the risk of rs13181 (ERCC2/XPD) polymorphism with the risk of Breast cancer have been controversial." (PMID 19615095, 2009). "Lastly, women with a waist-to-hip ratio (WHR) > 0.85 and homozygous for position 312 of ERCC2 exhibited a significant increase in the risk of breast cancer (OR = 1.96; 95% CI = 1.12–3.43)." (PMID 18454848, 2008).